NOMO2 (NODAL modulator 2)
Description:
Component of the multi-pass translocon (MPT) complex that mediates insertion of multi-pass membrane proteins into the lipid bilayer of membranes. The MPT complex takes over after the SEC61 complex: following membrane insertion of the first few transmembrane segments of proteins by the SEC61 complex, the MPT complex occludes the lateral gate of the SEC61 complex to promote insertion of subsequent transmembrane regions.
Synonyms: NOMO; PM5
Tractability: Antibody: UniProt predicts a signal peptide or a membrane-spanning region. PROTAC: ubiquitination databases record sites on it; its protein half-life has been measured.
Gene: Protein-coding gene on chromosome 16 (18,417,325 to 18,562,211, reverse strand). Ensembl gene ENSG00000185164.
Subcellular location: Endoplasmic reticulum membrane
Gene Ontology:
Molecular function: protein binding; ribosome binding; carbohydrate binding
Biological process: multi-pass transmembrane protein insertion into ER membrane
Cellular component: endoplasmic reticulum membrane; multi-pass translocon complex; protein-containing complex
Genetic constraint (gnomAD): Loss-of-function variants: 12 observed, 34.34 expected, observed/expected ratio (o/e) 0.35, 90% interval 0.22 to 0.57. The synonymous counts are far from expectation, so gnomAD's model fits this gene poorly and the ratio says little. Missense variants: 165 observed, 397.47 expected, observed/expected ratio (o/e) 0.42, 90% interval 0.37 to 0.47. Synonymous variants: 71 observed, 144.67 expected, observed/expected ratio (o/e) 0.49, 90% interval 0.4 to 0.6.
Homologues: Orthologues: rat Nomo1 (93% identical), mouse Nomo1 (92% identical), tropical clawed frog nomo3 (78% identical), zebrafish nomo (69% identical), Drosophila melanogaster CG1371 (31% identical), Caenorhabditis elegans nra-4 (24% identical). Paralogues in human: NOMO3 (99% identical), NOMO1 (99% identical).
Diseases named in the same sentence as NOMO2 in open-access papers:
NOMO2 is named in the same sentence as 4 diseases in open-access papers, as found by Europe PMC text mining. Sharing a sentence is not in itself a finding about the gene and the disease. The quoted sentences say what the papers report.
lung carcinoma (2 papers, 2019 to 2022). "The NOMO2 gene is known as a diagnostic biomarker in radioresistance in human H460 lung cancer stem-like cells." (PMID 35938032, 2022). "NOMO2 together with three other genes has recently linked to radio-resistance and suggested as diagnostic biomarkers in radio-resistant human H460 lung cancer stem-like cells." (PMID 31323891, 2019).
COVID-19 (1 paper, 2021). A disease caused by infection with severe acute respiratory syndrome coronavirus 2. "Overall, the DCA also showed that Nomo1 is more beneficial in predicting the mortality of the patients with COVID-19 than Nomo2 in a validation cohort." (PMID 34733858, 2021).
NOMO2 also shares sentences with these, for which no sentence is quoted: cancer (1 paper); non-small cell lung carcinoma (1).